APOE (apolipoprotein E)
Diseases named in the same sentence as APOE in open-access papers (continued):
Sharing a sentence is not in itself a finding about the gene and the disease.
atherosclerosis (continued). "In vitro animal experiments found that inhibition of GPVI by soluble GPVI-Fc or anti-GPVI antibodies protects atherosclerosis in cholesterol-fed rabbits and ApoE−/− mice." (PMID 33371312, 2020). "The current study looked at the effect of 8 weeks supplementation (4–5 mg/day) with ribose-cysteine in the apoE-/- mouse model of atherosclerosis over a time period (20 weeks of age) at which disease develops." (PMID 32084149, 2020). "Mouse homologs of the selected peptides were searched using BLAST to test the potential role in the immune response during atherosclerosis development in apoE–/– mice." (PMID 32373127, 2020). "Consistently, overexpression of GDF-15 in macrophages significantly attenuated atherosclerotic lesions in the apoE knockout mouse model of atherosclerosis." (PMID 33115406, 2020). "Apolipoprotein knockout (ApoE KO) mice have been widely used to study atherosclerosis pathology and treatment." (PMID 32943715, 2020). "We constructed an APOE-/- mice model of atherosclerosis, and found that PTPN2 was dramatically decreased in inflammatory mice." (PMID 33411686, 2020). "Atherosclerosis prone ApoE-KO mice are shown to develop more severe atherosclerosis during germ-free conditions." (PMID 32352513, 2020). "ApoE−/− mice fed a western-type diet for 12 weeks were used as the atherosclerosis model, and berberine was administered by oral gavage." (PMID 32566106, 2020). "Plaques were larger in atherosclerosis-prone Svep1 haploinsufficient (ApoE−/−Svep1+/−) compared to Svep1 wild-type mice (ApoE−/−Svep1+/+) and ApoE−/−Svep1+/− mice displayed elevated plaque neutrophil, Ly6Chigh monocyte, and macrophage numbers." (PMID 33185739, 2020). "The vascular protection of acacetin was confirmed in diabetes-accelerated atherosclerosis in STZ-diabetic ApoE−/− mice with an attenuated vascular lesion progression without affecting blood glucose." (PMID 33519472, 2020). "ApoE-/- rabbits were designed as a model for investigating the relationship between atherosclerosis and human hyperlipidemia." (PMID 32428130, 2020). "Neutrophils play an important role in all stages of atherosclerosis and neutrophil depletion studies in atherosclerotic mice (ApoE-/-) showed a reduction in early atherosclerosis." (PMID 33574814, 2020). "We have shown in the current study that β-OHB exerts a protective effect, possibly via anti-inflammatory action, on both AD and atherosclerosis in HFD-fed ApoE−/− mice." (PMID 32069870, 2020). "A study involving atherosclerosis prone ApoE(-/-) mice showed that 5/6 nephrectomy followed by eight weeks of pCS administration resulted in greater development of atherosclerosis and vSMC proliferation as compared with control mice." (PMID 32887404, 2020). "The APOE*3-Leiden.CETP mice are prone to atherosclerosis development and respond well to hypolipidemic drugs." (PMID 31843957, 2020). "Studies were performed in apoE−/− mice to investigate the role of T cells reactive to the cationic antimicrobial peptide in atherosclerosis." (PMID 33123157, 2020). "Analysis of ETAR, SMA and MMP-9 mRNA expression during the diet-induced progression of atherosclerosis reveals marked differences between ApoE−/− and control animals." (PMID 33255872, 2020). "The antiatherogenic role of NO is supported by numerous studies on knockout mice for ApoE and other animal models of atherosclerosis." (PMID 33014272, 2020). "We generated intestine-specific Dgat1−/− mice on the ApoE−/− background (iDgat1−/−ApoE−/−) and determined cholesterol homeostasis and atherosclerosis development." (PMID 32882484, 2020). "In the cardiovascular system, NAMPT exacerbates atherosclerotic inflammation and promotes atherosclerosis development in ApoE mice." (PMID 33488923, 2020). "In a similar context, Wen and colleagues used an ApoE-/- mouse model of high fat diet and perivascular collar induced atherosclerosis to specifically visualize oxidized LDL-loaded foam cells." (PMID 32106607, 2020).
atherosclerosis (continued). "In order to investigate the pathogenesis of atherosclerosis, we constructed an APOE-/- mice model of atherosclerosis." (PMID 33411686, 2020). "Rabbit models of atherosclerosis became less frequently used since 2000, when apolipoprotein E (apoE) and low-density lipoprotein (LDL) receptor knock-out mice were developed." (PMID 32428130, 2020). "Bilberry extract, also rich in anthocyanins, has been also shown to favorably alter genes related to the development of atherosclerosis in ApoE−/− mice." (PMID 32664664, 2020). "This changed not only with development of the ApoE−/−Fbn1C1039G+/− and Il1r1−/−ApoE−/− but also the tandem stenosis (TS) mouse model, which can mimic various stages of human atherosclerosis, including type VI lesion rupture." (PMID 32714944, 2020). "In this study, we constructed an APOE-/- mice model of atherosclerosis to research the molecular mechanism of atherosclerosis." (PMID 33411686, 2020). "In the present study, the atherosclerotic plaque area was significantly larger in ApoE-/- mice fed with a Western diet than that in normal chow-fed ApoE-/- mice, and L. mucosae A1 treatment reversed this trend of atherosclerosis." (PMID 32806628, 2020). "ApoE-KO mice develop severe atherosclerosis on a fat-containing diet, shortly became a powerful tool in atherosclerosis research." (PMID 32382308, 2020). "Most of them are based on genetic modifications of key genes involved in atherosclerosis development, such as apolipoprotein E or LDL receptor genes." (PMID 32428130, 2020). "ApoE-/- and ApoE-/-/Foxp3DTR mice were used to establish an atherosclerosis model by consuming a high-cholesterol diet according to several reports." (PMID 32977607, 2020). "PON1 is associated with high-density lipoprotein (HDL), and its overexpression has a protective effect against atherosclerosis in apoE-/- mice." (PMID 32245238, 2020). "Although CK reportedly showed anti-atherosclerosis effect in ApoE-/- mice, its mechanism remains ambiguous and needs to be elucidated." (PMID 33041808, 2020). "An important feature of apoE-/- mice is the ability to develop atherosclerosis even while being fed standard rodent chow diets." (PMID 32428130, 2020). "Genetic depletion of NEXN-AS1 dramatically increased atherosclerosis in ApoE–/– mice, with concurrent increases in markers of vascular inflammation such as VCAM-1, ICAM-1, TNF-α, and MCP-1." (PMID 33021969, 2020). "Our study is in keeping with previous studies showing that NAC inhibits atherosclerosis in apoE-/- mice." (PMID 32084149, 2020). "Studies in apoE-/- mice showed that decrease of aortic content of F2-isoprostanes and alleviation of atherosclerosis occurred in response to overexpression of catalases in combination with SOD-1." (PMID 32245238, 2020). "The importance of Gpx1 activity is very apparent in apoE-/-/Gpx1-/-mice which display greatly accelerated atherosclerosis development, which is attenuated by treatment with the GPx mimetic, ebselen." (PMID 32084149, 2020). "Modern techniques allowed creating more reliable rabbit models of atherosclerosis, such as Watanabe hereditary hypercholesterolemic animals, apolipoprotein E knock-out (ApoE-/-) animals, and diet-induced atherosclerotic New Zealand White rabbits." (PMID 32428130, 2020). "To investigate the potential role of T cells that are self-reactive to the cationic antimicrobial peptide in atherosclerosis, we used the apoE−/− mouse model of atherosclerosis and immunization with the mouse ortholog of LL-37 called mCRAMP." (PMID 33123157, 2020). "Further research of cardioprotection in ApoE−/− mice would be informative and aid the translation of therapeutic strategies into patients with atherosclerosis." (PMID 33258000, 2020). "Systemic delivery of miRNAs that inhibit NF-κB activation in the vascular endothelium also reduced inflammation and atherosclerosis lesions in ApoE–/– mice." (PMID 33021969, 2020).
atherosclerosis (continued). "Oxidative stress and endothelial dysfunction are implicated in the pathogenesis of numerous cardiovascular diseases including hypercholesterolemia and atherosclerosis in humans and in ApoE knockout mice." (PMID 32967121, 2020). "miR-155 and ApoE simultaneous knockout results in mice showing a decrease in atherosclerosis development but with increased obesity and aggravated NAFLD, suggesting that an increase of this miRNA is only detrimental in vascular tissue." (PMID 33102495, 2020). "Expectedly, our data demonstrated that AsC ameliorated plaque area in atherosclerosis in HFD-fed ApoE-/- mice." (PMID 31986489, 2020). "We first examined the expression of LOC285194 in aortic atherosclerotic plaques of ApoE-/- mice fed a high-fat diet, a widely used animal model of atherosclerosis." (PMID 31884873, 2020). "Several mimetics of apoA-I and apoE have succeeded in preventing atherosclerosis in animal models; however, human clinical trials involving ApoA-I apolipoprotein mimetic peptides have failed to prove a clinical benefit." (PMID 32485898, 2020). "We confirmed that T cells reactive to mCRAMP are functionally involved in atherosclerosis by the adoptive transfer of enriched T cells from mCRAMP-primed apoE−/− mice into recipient apoE−/− mice." (PMID 33123157, 2020). "The ApoE knockout mouse (ApoE−/−) model is widely used to investigate the pathogenesis of atherosclerosis." (PMID 32967121, 2020). "Crucially, the ApoE−/− model has been used to demonstrate potential clinical efficacy for a number of current atherosclerosis treatments." (PMID 32669659, 2020). "The apoE−/− mice in atherosclerosis induced by angiotensin II (Ang II) reveal that CD47 expression is significantly increased and concentrated in the necrotic core during atherosclerosis development." (PMID 32733941, 2020). "Apolipoprotein E knock-out (apoE-/-) mice that are also heterozygous for superoxide dismutase (SOD2+/−) knockout are characterized by accelerated atherosclerosis development in the arterial branch points." (PMID 32245238, 2020). "To date, there is no mouse model with consistent plaque instability, while the ApoE−/− mouse mutant appears to be key to the development of a transgenic model that completely mirrors human atherosclerosis." (PMID 32714944, 2020). "Genetic reduction of LRP-1 in ApoE–/–/LysM-DKO-LRP1fl/+ mice restored atherosclerosis and confirmed the interaction between LRP1 and epsins in atherosclerosis." (PMID 33363178, 2020). "The ApoE−/− mouse model is commonly used for atherogenesis, especially for investigating smoking-related atherosclerosis, as well as CS-induced lung inflammation and emphysema." (PMID 32419906, 2020). "To explore the potential application value of PTPN2 on the treatment of atherosclerosis, we performed an in vivo assay in APOE-/- mice." (PMID 33411686, 2020). "We have demonstrated that apoJ mimetic peptide renders HDL anti-inflammatory in mice and monkeys and dramatically reduces atherosclerosis in apolipoprotein E-null mice." (PMID 32462055, 2020). "Our results show that the immunoproteasome subunit LMP10 promoted diet-induced atherosclerosis in ApoE ko mice possibly through regulation of NF-κB-mediated macrophage polarization and inflammation." (PMID 33195259, 2020).
atherosclerosis (continued). "This study aimed to evidence the influence of amygdalin on high-fat diet-induced atherosclerosis in ApoE knock-out (ApoE−/−) mice, and unravel its anti-inflammatory mechanism." (PMID 33192531, 2020). "Previous studies in T1D model by streptozotocin injection in apolipoprotein E-deficient mice have proved that NBD peptide administration ameliorates diabetic kidney damage and atherosclerosis through the modulation of systemic and local inflammation." (PMID 32545818, 2020). "In summary, we have preliminary studied the molecular mechanism of atherosclerosis by constructing an APOE-/- mice model." (PMID 33411686, 2020). "A different study displays that ApoE-/- mice subjected to atherosclerosis show decreased lesion sites when IL-1β is blocked." (PMID 32545788, 2020). "In ApoE*3 leiden mice fed a high cholesterol diet, fenofibrate reduces atherosclerosis more than can be explained by the lowered total plasma cholesterol." (PMID 32321551, 2020). "To evaluate the functions of APE1/Ref-1 in atherosclerosis, we selected ApoE−/− mice as our animal model of atherosclerosis." (PMID 32967121, 2020). "Another study has evaluated the effect of dietary vitamin E supplementation in apoE-/- mice and demonstrated its beneficial effects on atherosclerosis development." (PMID 32428130, 2020). "Although ApoE and its specific isoforms have long been known to play a key role in lipid transport and atherosclerosis, the role of apoE in human cancers is not well understood." (PMID 32462055, 2020). "To observe atherosclerosis with CIH exposure, we fed ApoE-deficient mice with a high-fat diet under CIH or normoxia conditions." (PMID 32328084, 2020). "Atherosclerosis and chronic inflammation model mice (Prdx1−/−;ApoE−/−) show increased formation of atherosclerotic plaque compared with Prdx1+/+;ApoE−/− mice." (PMID 32098329, 2020). "In this study, we found that kcnq1ot1 dramatically reduces RCT and aggravates atherosclerosis in apoE−/− mice." (PMID 33293505, 2020). "So, the ApoE−/− mouse is widely used in the research for atherosclerosis as it can manifest pathological features of human atherosclerosis." (PMID 33193911, 2020). "In the ECs of apolipoprotein E (ApoE)−/− atherosclerosis model mice, antiapoptotic Bcl-2 was significantly decreased while caspase-3 was significantly increased." (PMID 32963706, 2020). "ApoE−/− mice lacking CD4+ T cells were found less susceptible to atherosclerosis compared with wild-type mice, and transfer of CD4+ T cells to immunodeficient ApoE−/− mice significantly promoted atherosclerosis." (PMID 32460698, 2020). "Improvement of endothelial function in atherosclerosis model reduces T-cells, macrophages and monocytes infiltration into plaques of ApoE–/– mice." (PMID 33329050, 2020). "In the present study, ex vivo 14T-MR imaging was used to quantify the extent of atherosclerosis in the aortas of ApoE−/− mice enabling the visualization, and subsequent quantification of total plaque volume with sensitivity." (PMID 32717800, 2020). "In animal studies, treatment with recombinant human IL-35 led to an increase in both circulating and local Treg levels and a reduction in the plaque size in ApoE−/− mice, suggesting that IL-35 attenuates atherosclerosis via upregulating Treg immune response." (PMID 33193911, 2020). "In ApoE-/- mice fed with a Western diet, this strain reduced the accumulation of triglyceride in serum and liver, alleviated the development of atherosclerosis, and shifted the structure of gut microbiota." (PMID 32806628, 2020).
atherosclerosis (continued). "RT-PCR analysis detected the mRNA levels of collagen I and α-SMA and we found that silencing of miR-520a-3p showed significant increase of mRNA levels of collagen and α-SMA in lesions in apoE-/- mice with atherosclerosis." (PMID 33768113, 2020). "Relevance of identified self-antigens to atherosclerosis, the major underlying cause of CAD, was tested in the apoE–/– atherosclerotic mouse model." (PMID 32373127, 2020). "As a result, in ApoE knockout mice fed with a high-cholesterol diet, supplementation with 0.3% of SalB for 3 months protects mice from atherosclerosis by reducing vascular intimal thickness, accompanied by decreasing COX-2, MMP-2, and MMP-9 expression." (PMID 33062143, 2020). "Our data demonstrated for the first time that the immunoproteasome subunit LMP10 promoted diet-induced atherosclerosis in ApoE ko mice partially through regulation of NF-κB-mediated macrophage polarization and inflammation." (PMID 33195259, 2020). "The purposes of this study were to observe the effects of high or low doses of BBR on atherosclerosis and gut microbiota modulation, and to explore their correlation in ApoE–/– mice fed a high-fat diet." (PMID 32231564, 2020). "In contrast, kcnq1ot1 knockdown protected against atherosclerosis in apoE−/− mice and suppressed lipid accumulation in THP-1 macrophages." (PMID 33293505, 2020). "In vivo, we established the atherosclerosis model by feeding APOE−/− mice with high fat diet for 12 weeks." (PMID 32792941, 2020). "ApoE−/− mice are ideal animal models for hyperlipidemia and atherosclerosis, and their vascular pathophysiological changes are similar to human." (PMID 33644113, 2020). "To further validate this conclusion, we constructed an atherosclerosis mouse model by feeding ApoE–/– mice with a high-fat diet for 25 weeks." (PMID 32714363, 2020). "To confirm our results in vivo, we took advantage of the ApoE-KO mouse, one of the most widely used models to study atherosclerosis." (PMID 32231663, 2020). "In an early study, the relationship between atherosclerosis and hypertension was noted in ApoE−/− mice." (PMID 32630530, 2020). "The present study demonstrates the novel information that acacetin provides strong protection against high glucose-induced vascular endothelial injury and attenuates diabetes-accelerated atherosclerosis in STZ-diabetic ApoE−/− mice." (PMID 33519472, 2020). "On the contrary, overexpression growth hormone exacerbated atherosclerosis in apolipoprotein E KO mice." (PMID 33209195, 2020). "The present data demonstrate the positive health benefits of chronic peptide 4D administration to the atherosclerosis-prone ApoE-/- mice, and provides new information for potential use of this F11R derived peptide in the prevention of atherosclerosis." (PMID 32395574, 2020). "The recently developed apoE*3‐Leiden.CETP (E3L.CETP) mouse model of atherosclerosis appears to be the one that most closely replicates the features of human disease." (PMID 32428130, 2020). "A study revealed that atherosclerosis in SIRT1+/‐Apo E−/− mice is decreased significantly compared with ApoE−/− counterparts." (PMID 32627301, 2020). "In this experiment, to investigate the role of nicotine in the progression of atherosclerosis, the ApoE-/- mice were divided into two groups: a control group which drinks normal water and a nicotine group which drinks water containing nicotine." (PMID 32373212, 2020). "A PubMed search (March 14, 2020) of “nicotine AND ApoE” yielded only 41 results, while a search of “cigarette smoke AND ApoE AND atherosclerosis” yielded 46 results." (PMID 32331221, 2020). "Vessels from ApoE-/- mice were collected after 12 weeks feeding of a control or high fat diet, with the latter being an established method to reproducibly promote atherosclerosis." (PMID 32208424, 2020). "In the past few decades, the crucial role of APOE in the pathogenesis of atherosclerosis has been recognized." (PMID 32546237, 2020).